TRDJ1 (T cell receptor delta joining 1)
Description:
J region of the variable domain of T cell receptor (TR) delta chain that participates in the antigen recognition. Gamma-delta TRs recognize a variety of self and foreign non-peptide antigens frequently expressed at the epithelial boundaries between the host and external environment, including endogenous lipids presented by MH-like protein CD1D and phosphoantigens presented by butyrophilin-like molecule BTN3A1. Upon antigen recognition induces rapid, innate-like immune responses involved in pathogen clearance and tissue repair. Binding of gamma-delta TR complex to antigen triggers phosphorylation of immunoreceptor tyrosine-based activation motifs (ITAMs) in the CD3 chains by the LCK and FYN kinases, allowing the recruitment, phosphorylation, and activation of ZAP70 that facilitates phosphorylation of the scaffolding proteins LCP2 and LAT. This lead to the formation of a supramolecular signalosome that recruits the phospholipase PLCG1, resulting in calcium mobilization and ERK activation, ultimately leading to T cell expansion and differentiation into effector cells. Gamma-delta TRs are produced through somatic rearrangement of a limited repertoire of variable (V), diversity (D), and joining (J) genes. The potential diversity of gamma-delta TRs is conferred by the unique ability to rearrange (D) genes in tandem and to utilize all three reading frames. The combinatorial diversity is considerably increased by the sequence exonuclease trimming and random nucleotide (N) region additions which occur during the V-(D)-J rearrangements.
Synonyms: TCRD
Gene: T-cell receptor joining (J) gene on chromosome 14 (22,450,089 to 22,450,139, forward strand). Ensembl gene ENSG00000211825.
Subcellular location: Cell membrane
Gene Ontology:
Cellular component: plasma membrane